ENSG00000285082 (novel protein)
Gene: Protein-coding gene on chromosome 9 (117,704,157 to 118,083,691, forward strand). Ensembl gene ENSG00000285082.
Genetic constraint (gnomAD): Loss-of-function variants: 0 observed, 3.67 expected, observed/expected ratio (o/e) 0, 90% interval 0 to 0.81. That is too few expected variants to judge how well the gene tolerates losing a copy. Missense variants: 37 observed, 42.77 expected, observed/expected ratio (o/e) 0.87, 90% interval 0.66 to 1.14. Synonymous variants: 11 observed, 16.69 expected, observed/expected ratio (o/e) 0.66, 90% interval 0.41 to 1.09.